MALT1 (MALT1 paracaspase)
Diseases named in the same sentence as MALT1 in open-access papers (continued):
Sharing a sentence is not in itself a finding about the gene and the disease.
lymphoma (52 papers, 2010 to 2026). A malignant (clonal) proliferation of B- lymphocytes or T- lymphocytes which involves the lymph nodes, bone marrow and/or extranodal sites. "Mucosa-associated lymphoid tissue lymphoma-translocation protein 1 (MALT1) is an attractive target for the development of modulatory compounds in the treatment of lymphoma and other cancers." (PMID 39014105, 2024). "In the present study, MALT1 mutations in the ctDNA were also found in patients with lymphoma and were only found in patients with GCB." (PMID 35865478, 2022). "Mutation of E549 into alanine (E549A) led to complete loss of the enzymatic activity of MALT1, and to a consequent loss of the growth-promoting function of MALT1 in lymphocytes and lymphoma cells." (PMID 23977204, 2013). "Enhanced expression of MALT1 has been linked to the development of leukemia and lymphoma." (PMID 34926571, 2021). "The up‐regulation of MALT1 is linked to the development of leukaemia and lymphoma." (PMID 32452133, 2020). "MALT1 protease inhibitors might prove especially valuable in the treatment of lymphomas that harbor mutations in signaling effectors downstream of BTK or that have acquired resistance towards BTK inhibition." (PMID 29587428, 2018). "Here, we demonstrate that depletion of BLM (phenocopied by the inhibition of MALT1) suppresses the progression of lymphoma and leukaemia by inhibiting MALT1-dependent NF-κB signalling and sensitizing malignant B cells to chemotherapy." (PMID 42156715, 2026). "Our findings demonstrate that small-molecule inhibitors of BCL10-MALT1 interaction can function as potent agents to block MALT1 signaling in selected lymphomas, and provide a road map for clinical development of a new class of precision-medicine therapeutics." (PMID 40231473, 2025). "As a key regulator of adaptive immune responses, MALT1 represents a clear target for developing modulatory/inhibitory compounds to treat lymphoma, cancers, and autoimmune diseases." (PMID 39014105, 2024). "The MALT1 is a critical regulator of cytokine and antigen receptor signaling, and MALT1 inhibitors attenuate the pathology of rheumatoid arthritis, ulcerative colitis, lymphomas, spondylitis, autoimmunity, multiple sclerosis, etc.." (PMID 38519981, 2024). "Over a mean follow-up interval of 65 months, a significant predilection for lymphoma recurrence or disease relapse emerged in patients exhibiting increased copies of MALT1 through multivariate analysis in comparison to those without." (PMID 38418651, 2024). "The therapeutic targeting of MALT1 protease activity is a potential approach for the treatment of lymphomas or an effective strategy for treating neoplastic and inflammatory disorders associated with dysregulated NF-κB signaling." (PMID 37047218, 2023). "In other lymphomas, such as mantle cell lymphoma (MCL), chronic activation of BCR signaling and MALT1 activity have been detected, but the molecular cause currently remains elusive." (PMID 35203553, 2022). "MALT1 has been found have a vital role in lymphoma and immune cell development in the last two decades." (PMID 35309901, 2022). "Since numerous reviews have highlighted the role of MALT1 in hematological malignancies, this review mainly focuses on the importance of MALT1 in solid tumors and only briefly summarizes its role in lymphoma and leukemia development." (PMID 35203553, 2022). "In almost all different types of lymphoma, MALT1 is required to cleave NF-κB negative regulators A20 and RelB, while it is less studied in solid tumors." (PMID 35309901, 2022). "The MI-2 (2-Chloro-N-[4-[5-(3,4-dichlorophenyl)-3-(2-methoxyethoxy)-1H-1,2,4-triazol-1-yl]phenylacetamide]) has been demonstrated as a MALT1 inhibitor which decreases MALT1-induced NF-κB activity in lymphoma (ABC-DLBCL) and cholangiocarcinoma cells." (PMID 33802402, 2021).
lymphoma (continued). "Further investigation unveiled a potential function of GRK2 as an onco-modulator/tumor suppressor by blocking MALT1 activity in MALT1-dependent lymphomas." (PMID 33546162, 2021). "Pre‐clinical animal experiments have shown that MI‐2 is a MALT1 inhibitor that can avert lymphoma progression." (PMID 32452133, 2020). "Given its central role downstream of multiple immune receptors, the MALT1 protease is an attractive therapeutic target for a variety of indications spanning from autoimmunity to lymphomas." (PMID 32425939, 2020). "Because of its role in lymphocyte activation and proliferation, inhibition of MALT1 proteolytic activity is of high interest for therapeutic targeting in autoimmunity and certain lymphomas." (PMID 31474984, 2019). "c-Rel activation requires MALT1′s function as a protease, as MI-2, an irreversible direct enzymatic inhibitor of MALT1, was shown to inhibit c-Rel nuclear translocation in human lymphoma cell lines in vitro and in a xenograft mouse model." (PMID 31277480, 2019). "Activating mutations of PLCG1 increasing the transcriptional activity of NF-κB via induction of MALT1 protease activity were also found in angioimmunoblastic T-cell lymphoma and other lymphomas derived from follicular T-helper cells." (PMID 30718475, 2019). "In some types of lymphomas, constitutive MALT1 activation is achieved by mechanisms that bypass the classical CBM signaling events." (PMID 30214442, 2018). "Third, what is the role of MALT1 proteolytic activity, which is required for the survival of lymphoma cells harboring B-cell receptor or CARMA1 gain-of-function mutations, in tumors characterized by GPCR or RTK-driven CARMA3 activation?" (PMID 30158935, 2018). "MALT1 targeting with mepazine and other small compound inhibitors has recently been shown to hold significant potential in the treatment of lymphoma." (PMID 25043939, 2014). "Third, continuous MALT1 auto-proteolysis was observed in ABC-DLBCL cells and SSK41 MALT lymphoma cells that have constitutive MALT1 protease activity." (PMID 25105596, 2014). "Few studies have focused on the expression characteristics of A20, its regulatory factor MALT1 and NF-κB in patients with lymphomas and evaluated immune function in patients." (PMID 24790527, 2014). "Next, we sought to determine whether M1i-124 and M1i-124d1 exhibit selective cytotoxicity against MALT1-dependent lymphoma cells." (PMID 40231473, 2025). "Besides genetic alterations of components of the CBM signalosome, constitutive antigen receptor signaling is a major driver for chronic MALT1 activation and thus for lymphoma development." (PMID 35203553, 2022). "The mucosa-associated lymphoid tissue 1 gene (MALT1) modulates NF-κB signal transduction in lymphoma and non-lymphoma cells." (PMID 35053438, 2022). "It is explicit that MALT1 activates the NF-κB pathway through the CBM complex in lymphoma." (PMID 35309901, 2022). "In our study, we found ECOG score 3–4 was closely associated with mutations in MYD88, MALT1, and ROS1, which suggested that ECOG might be associated with lymphoma heterogeneity." (PMID 35865478, 2022). "Indeed, MALT1 promotes cancer malignant progression not only in lymphoma but also in other types of cancer, such as melanoma and lung cancer." (PMID 35309901, 2022). "Therefore, therapeutic targeting of MALT1 protease activity is a potential approach for the treatment of lymphomas or as an effective strategy for treating those neoplastic and inflammatory disorders which associated with dysregulated NF-κB signaling." (PMID 33802402, 2021). "Furthermore, the increased detection of genetic aberrations frequently observed in B-cell lymphomas, including BCL2, BCL6, IGH, and MALT1 translocations, should promote the development of lymphoma gene panels for BALF in the era of next-generation sequencing." (PMID 34873224, 2021).
lymphoma (continued). "In addition to this newly described role in MALT1-dependent lymphoma, protein-protein interactions involving GRK2 have also been implicated as influencing the pathogenesis of the related B-cell malignancy, chronic lymphocytic leukemia (CLL)." (PMID 33546162, 2021). "In addition, the lymphoma cells carrying IGH/MALT1 show not only over-expression of MALT1, but also BCL10 accumulation in cytoplasm." (PMID 35008340, 2021). "Studies suggested that MALT1 overexpression in lymphoma could result from gene translocation, form MALT1-fusion proteins, and activate the NF-κB pathway." (PMID 33802402, 2021). "Chromosome 18 includes the gene MALT1, which encodes a caspase-like protease that plays a role in BCL10-induced activation of the NF-κB pathway and thus, the overexpression of MALT1 as seen in trisomy 18 has been associated with lymphoma progression." (PMID 33804823, 2021). "Therefore, MALT1 has been proposed to be a promising therapeutic target for the treatment of lymphomas and autoimmune disorders." (PMID 34926571, 2021). "Therefore, MALT1 is currently considered as a promising therapeutic target for treating lymphomas and autoimmune disorders." (PMID 32452133, 2020). "Finally, an increasing number of publications support a role for aberrant MALT1 signaling in the development of non-lymphoid cancers, such as glioblastoma, breast cancer, melanoma, lung cancer, and various other carcinomas." (PMID 30214442, 2018). "Indeed, pharmacological inhibition of the MALT1 protease function has been reported to exert selective toxicity towards MALT1-dependent lymphomas both in vitro and in vivo using xenograft mouse models." (PMID 29587428, 2018). "Moreover, the MALT1 expression level was downregulated in all three lymphoma subtypes." (PMID 24790527, 2014). "Moreover, our findings support the idea that small molecule compounds specifically targeting the MALT1 dimerization interface could be useful as immunosuppressant or anti-lymphoma agents." (PMID 23977204, 2013). "Differentially regulated genes were enriched for classical lymphoma driver genes downstream of the BCR, including MALT1 and CARD11, as well as NFATC2, TNFRSF13C (BAFF), and components of the NF-κB (RELB, IRAK1, BCL3, and TNFRSF1B) pathway." (PMID 39082968, 2024). "Ectopic overexpression of WT CYLD or a MALT1-cleavage resistant mutant of CYLD reduced NF-κB activity and growth of BCR-dependent lymphoma cell lines." (PMID 36922488, 2023). "In lymphoma cells, knockout of GRK2 leads to enhanced MALT1-mediated IκB phosphorylation, RELB and CYLD cleavage, cytokine secretion, and cell proliferation, and GRK2 rescue reverses these effects." (PMID 34917606, 2021). "In these lymphoma cells the CBM complex is constitutively assembled, resulting in strong MALT1 protease activity and NF-κB activation." (PMID 28052131, 2017). "Further, MALT1 protease activity drives the survival of aggressive lymphomas and other non-hematologic solid cancers." (PMID 38863711, 2024). "Ectopic overexpression of WT CYLD or a MALT1-cleavage resistant mutant of CYLD reduced phosphorylation of IκBα, repressed transcription of canonical NF-κB target genes and impaired growth of BCR-dependent lymphoma cell lines." (PMID 36922488, 2023). "Lastly, precisely how GRK2 influences the functionality of its interaction partners in lymphocytes including TCR CD3ε, MALT1, RKIP, etc., are important questions whose answers will advance our understanding of normal immune response as well as the pathogenesis of lymphoid cancers." (PMID 33546162, 2021). "Potential treatment of lymphomas with a MALT1 inhibitor has been contemplated based on numerous studies showing that MALT1 protease function is a key driver for proliferation of e.g., ABC-DLBCL lymphomas and MALT1 protease inhibitors are now entering clinical trials for these indications." (PMID 32425939, 2020).
lymphoma (continued). "While MALT1 activity has not yet been assessed in other lymphoma types, it seems likely that additional types of B- or T-cell lymphomas with constitutive antigen receptor signaling are sensitive to MALT1 inhibition." (PMID 26507244, 2016). "To assess whether MALT1-mediated CYLD cleavage directly contributes to growth of BCR-dependent lymphoma cell lines, we generated a CYLD mutant that can no longer be cleaved by MALT1 (CYLD R324 A)." (PMID 36922488, 2023). "The data demonstrated that MALT1 PROTACs induce MALT1 degradation in the human diffuse large B-cell lymphoma cell line OCI-Ly3, suggesting that MALT1 PROTACs may be excellent drugs for the treatment of ABC-DLBCL and other lymphomas." (PMID 36142231, 2022). "Aberrant induction of MALT1 protease activity is a major consequence of constitutive CBM signaling and has been reported to be essential for the survival of several lymphoid malignancies, such as ABC DLBCL, MCL, and CLL, making MALT1 an attractive therapeutic target in lymphoma treatment." (PMID 29587428, 2018). "In this review, we discuss how post-translational modifications, such as phosphorylation and ubiquitination of the CBM components, as well as, MALT1 proteolytic activity, shape the CBM activity in lymphocytes and ABC DLBCL, and may provide new avenues to restore vulnerability in lymphoma." (PMID 30474008, 2018). "It will be interesting to unravel whether MALT1 may be active in other Ibrutinib sensitive lymphomas such as CLL or MCL and to determine whether combinatorial BTK and MALT1 inhibition may potentially hold benefits for lymphoma patients beyond ABC DLBCL." (PMID 26540570, 2015). "An abnormal MALT1-A20-NF-κB expression pattern was found in patients with lymphoma, which may result a lack of A20 and dysfunctional MALT1 and may be related to lower T cell activation, which is a common feature in Chinese patients with lymphoma." (PMID 24790527, 2014). "Although the distinct mechanisms of MALT1 in cancer progression may be quite different from lymphomas, the oncogenic role and therapeutic potential of MALT1 have been well demonstrated in several non-lymphoid solid tumors, including breast cancer, lung cancer, melanoma, and cholangiocarcinoma." (PMID 33802402, 2021). "Since differences in MALT1 protein expression do not account for the observed differences in cleaved CYLD levels, this suggests that post-translational regulation of MALT1 activity, not MALT1 expression as such, determines CYLD cleavage in lymphoma cell lines." (PMID 36922488, 2023). "Surprisingly, MALT1 substrates, such as Roquin1/2 and Regnase have not been studied in the context of ABC DLBCL and whether MALT1 aberrant activation modulates the stability of mRNAs in this subtype of lymphoma is unknown." (PMID 30474008, 2018).
diffuse large B-cell lymphoma (30 papers, 2013 to 2026). "Aberrant activation of MALT1 is implicated in the pathogenesis of hematologic malignancies, particularly diffuse large B-cell lymphoma, and select solid tumors." (PMID 41783325, 2026). "The novel MALT1-MAP4 fusion protein, which is different from the known MALT1-associated chromosomal rearrangements, may be a new pathogenetic reason of diffuse large B-cell lymphoma." (PMID 29743960, 2018). "To investigate endogenous MALT1 regulation, we first looked into human activated B cell-like diffuse large B-cell lymphoma (ABC-DLBCL) cells, which are characterized by chronic active B-cell receptor signalling." (PMID 28052131, 2017). "Exaggerated MALT1 activity has been associated with the development of lymphoid malignancies, and recently developed MALT1 inhibitors show promising anti-tumor effects in xenograft models of diffuse large B cell lymphoma." (PMID 26507244, 2016). "Mucosa-associated lymphoid tissue lymphoma translocation protein 1 (MALT1) is a unique paracaspase protein whose protease activity mediates oncogenic NF-κB signalling in activated B cell-like diffuse large B cell lymphomas (ABC-DLBCLs)." (PMID 26788853, 2016). "At the cellular level, MALT1 proteolytic activity has been implicated in MALT lymphoma and activated B cell-like diffuse large B cell lymphoma (ABC-DLBCL)." (PMID 25043939, 2014). "MALT1 protease activity is also essential for the survival of cells derived from the activated B-cell subtype of diffuse large B-cell lymphoma (ABC-DLBCL), which are addicted to constant MALT1-driven NF-κB signaling." (PMID 25105596, 2014). "Moreover, MALT1-mediated NF-κB signaling plays a key role in the proliferation of certain B cell lymphomas, such as MALT1 lymphoma and activated B cell-like diffuse large B cell lymphoma (ABC-DLBCL)." (PMID 31632405, 2019). "MI-2 which was shown to bind directly to MALT1 and acted as an irreversible inhibitor, could suppress the growth of activated B cell-like diffuse large B cell lymphoma (ABC-DLBCL) in both in vitro and in vivo assays." (PMID 29371921, 2017). "Recent studies have found that MALT1 has therapeutic targeting in ABC-type diffuse large B-cell lymphoma (ABC-DLBCL)." (PMID 36142231, 2022). "A study reported that, as novel MALT1 inhibitors, β-lapachone analogs exhibited potent antiproliferative activity and inhibited the cleavage of CYLD mediated MALT1; this may be a promising therapeutic target for the treatment of aggressive subtype of diffuse large B-cell lymphoma." (PMID 29259980, 2017). "CK1α is a tumor supporter in diffuse large B cell lymphoma (DLBCL) of activated B cell subtype, inducing the activation of NF-κB through the regulation of the CBM1 complex (CARD11, BCL10, MALT1)." (PMID 28969692, 2017). "A tumor-promoting role of MALT1 has first been found in MALT lymphoma and activated B cell-like diffuse large B cell lymphoma (ABC-DLBCL)." (PMID 27105502, 2016). "Furthermore, in diffuse large B-cell lymphoma (DLBCL) and mantle cell lymphoma (MCL), CK1α contributes to the constitutive activation of the NFκB pathway along with the CARD11/BCL10/MALT1 (CBM) complex." (PMID 38265263, 2024). "The first indication that Malt1 inhibition might be a promising strategy to treat human diseases came from two studies in 2009 which reported a preferential cytotoxicity of the MALT1 inhibitor z-VRPR-fmk on a subtype of cell lines derived from diffuse large B-cell lymphoma (DLBCL)." (PMID 26507244, 2016). "The aggressive activated B-cell like (ABC) subtype of diffuse large B-cell lymphoma (DLBCL) exploits a multi-protein complex of CARMA1, BCL10, and MALT1 (CBM complex), which normally conveys NF-κB signaling upon antigen receptors engagement." (PMID 30474008, 2018). "MALT1, which removes HOIL-1L RBR domain from LUBAC by cleaving HOIL-1L between Arg165 and Gly166, is activated in most activated B-cell-like diffuse large B-cell lymphoma (ABC-DLBCL)." (PMID 34685685, 2021).
diffuse large B-cell lymphoma (continued). "However, application of a targeted therapeutic approach involving the CARD11–BCL10-MALT1 (CBM) signaling pathway or drugs like lenalidomide which are used for diffuse large B cell lymphomas (DLBCL) and MALT1 protease inhibitors may help in the better management of BENTA patients in the near future." (PMID 29963038, 2018).